ZEB1 (zinc finger E-box binding homeobox 1)
Diseases named in the same sentence as ZEB1 in open-access papers (continued):
Sharing a sentence is not in itself a finding about the gene and the disease.
pancreatic cancer (continued). "By modulating SIRT3 expression, ZEB1 not only drives aerobic glycolysis but also contributes to the broader metabolic flexibility and survival of pancreatic cancer cells under the hypoxic and nutrient-poor conditions leading to alterations in the tumor microenvironment." (PMID 39682281, 2024). "Moreover, ZEB1, a zinc finger E-box binding homeobox transcription factor, is crucial for the EMT process and abnormal expression of ZEB1 has been reported in pancreatic cancer." (PMID 36902253, 2023). "Moreover, miR-4269 overexpression inhibits pancreatic cancer cell proliferation, migration, and invasion by affecting the E-box binding homeobox 1 (ZEB1)/OTX1 pathway." (PMID 38069286, 2023). "Additionally, lincRoR promoted cell proliferation of pancreatic cancer through the elevation of ZEB1." (PMID 36986051, 2023). "Zeb1 downregulation in mouse PSCs retarded the expansion of stromal myofibroblasts during precursor-to-cancer progression and interfered with their functions to foster the growth of pancreatic cancer cells." (PMID 37174079, 2023). "Indeed, the depletion of ZEB1 suppressed stemness, colonization capacity, and in particular phenotypic/ metabolic plasticity of pancreatic cancer cells." (PMID 38139138, 2023). "In the context of pancreatic cancer, ZEB1 stands out as a significant contributor to the EMT because of its ability to seamlessly transition between a transcriptional repressor and activator, depending on how it interacts with co-activators like Lef1, YAP1, P300, and Smad." (PMID 38139352, 2023). "In these pancreatic cancer cells, high glucose influx elevates the level of O-GlcNAcylation on ZEB1, a key transcription factor involved in tumor development, at serine residue 555, which promotes ZEB1 stabilization and nuclear localization." (PMID 37838167, 2023). "Similarly, XIST regulates ZEB1 expression in pancreatic cancer by sponging miRNA-429 to promote migration, invasion, and EMT." (PMID 36038831, 2022). "In pancreatic cancer, miR-652 inhibits epithelial-mesenchymal transition by targeting ZEB1." (PMID 35111226, 2022). "LncRNA-ROR also facilitates pancreatic cancer metastasis by acting on the ZEB1 pathway." (PMID 35819532, 2022). "LncRNA-BX111, induced by hypoxia, was overexpressed in pancreatic cancer and could promote the metastasis and progression of pancreatic cancer by regulating the transcriptional regulatory factor ZEB1." (PMID 35819532, 2022). "In this study, we confirmed that glucose could rescue Erastin and RSL3 induced mesenchymal pancreatic cancer cells ferroptosis depending on O-GlcNAcylation modification of ZEB1 in vitro and in vivo." (PMID 35844792, 2022). "Moreover, O-GlcNAcylation enhanced mesenchymal pancreatic cancer cells ferroptosis was diminished in ZEB1 knockdown cells." (PMID 35844792, 2022). "Furthermore, ZEB1 downregulation through HDAC class I inhibition or DNA demethylation resensitizes pancreatic cancer and osteosarcoma cells to chemotherapy." (PMID 34459003, 2021). "The LINC00472 expression was down‐regulated by ZEB1 in the pancreatic cancer cells and tissues." (PMID 34363438, 2021). "Moreover, nearly 64.3% of pancreatic cancer samples with higher expression of ZEB1 presented stronger ELK3 staining, while approximately 71.2% of those with lower ZEB1 expression exhibited weaker ELK3 staining." (PMID 34409034, 2021). "Initially, repressed transcription of LINC00472 by ZEB1 was identified in pancreatic cancer." (PMID 34363438, 2021). "To conclude, our data presented that LINC00472, a lncRNA down‐regulated by ZEB1 in pancreatic cancer, could function as tumour suppressor in pancreatic cancer, thus establishing the significance of LINC00472 as a therapeutic target against pancreatic cancer." (PMID 34363438, 2021).
pancreatic cancer (continued). "In addition, the protein level of ZEB1 was examined in above 70 paired pancreatic cancer tissues and paracancerous tissues, and the results of IHC analysis showed that ZEB1 was highly expressed in pancreatic cancer tissues compared with matched normal tissues." (PMID 34409034, 2021). "Correlations between ZEB1 and clinicopathologic parameters in pancreatic cancer patients." (PMID 34409034, 2021). "Similarly, GRHL2 regulates epithelial plasticity along with stemness in pancreatic cancer progression by forming a mutual inhibitory loop with ZEB1." (PMID 32266287, 2020). "To analyse whether an EMT is capable of altering the S100 expression profile in pancreatic cancer cells, we overexpressed ZEB1 in two epithelial PDAC cell lines, BxPC-3 and SU.86.86." (PMID 31123345, 2019). "Furthermore, ZEB1 was expressed in pancreatic cancer cells stably maintaining ahybrid E/M state for six months." (PMID 31069317, 2018). "Thus, expressions of Vimentin, Zeb1, and Snail were found to be downregulated upon rfhSP-D treatment in the pancreatic cancer cell lines." (PMID 30158928, 2018). "ZEB1 is indicated as a key factor for pancreatic cancer progression." (PMID 28649800, 2017). "According to the results of previous studies, USP22 can induce EMT by regulating TGF-β1 in lung cancer cells, and elevated USP22 expression can promote EMT by up-regulating ZEB1 and Snail in pancreatic cancer cells though a process that involves focal adhesion kinase (FAK) signaling." (PMID 28427243, 2017). "This identified PEAK1, BMPR2, COL4A1 and ZEB1 as ITGA1 co-expressors in pancreatic cancer and suggested that ITGA1 may play a role in regulating TGFβ responses in pancreatic cancer." (PMID 28855593, 2017). "Four pancreatic cancer cell lines were examined for their basal expression of epithelial (E-cadherin, ZO-1) and mesenchymal markers (N-cadherin), as well as transcriptional repressors of E-cadherin (Snail-1 and Zeb-1)." (PMID 27764163, 2016). "Furthermore, the ZEB1 expression is also regulated through mTOR signaling pathways in cholangiocarcinoma and pancreatic cancer cells." (PMID 27150059, 2016). "Furthermore, ZEB1 expression was found to be significantly higher in pancreatic cancer tissues classified as Stage III or IV than Stage I or II (85.7 vs. 38.9%; p = 0.0024)." (PMID 26498682, 2015). "We speculate that the newly identified miRNA802 might be involved in the regulation of ZEB1 and consequently might promote the mesenchymal character of pancreatic cancer." (PMID 25910082, 2015). "According to the data of miRNAs-microarray and qRT-PCR validation in pancreatic cancer cells, the downregulated miR-652, predicted as the potential regulator for ZEB1 expression, was found to be one of the most attractive candidates functioning in acidic microenvironment." (PMID 26498682, 2015). "Recently, we reported similar observations for EMT induced by ZEB1 in pancreatic cancer." (PMID 24281177, 2010). "This article reviews the biological functions of ZEB1 with a focus on pancreatic cancer." (PMID 24281177, 2010). "For pancreatic cancer cells, antagonism between ZEB1 and stemness-inhibiting micro-RNAs has been demonstrated to contribute to this process, providing experimental support for the migrating cancer stem cell (MCSC) hypothesis." (PMID 24281177, 2010). "Furthermore, silencing of Zeb1 in pancreatic cancer cell lines led to the upregulation of E-cadherin and restoration of an epithelial phenotype." (PMID 24281219, 2010). "In pancreatic carcinoma, ZEB1 can be up-regulated by IKK/ NF-κB activation." (PMID 24281218, 2010). "In addition, Zeb1 is known to make human pancreatic cancer cells resistant to chemotherapy." (PMID 39070795, 2024).
pancreatic cancer (continued). "First, in pancreatic cancer, plasticity in switching between basic energy pathways is strongly compromised in Zeb1-depleted cancer cells, which display both decreased oxidative phosphorylation (OXPHOS) and a reduced glycolytic reserve; this plasticity might be critical for the colonization step." (PMID 35246504, 2022). "In addition, miR-128-3P targets ZEB1 to hinder invasion and migration in pancreatic cancer cells." (PMID 35805066, 2022). "In addition, lncRNA-BX111887 directly interacts with transcriptional factor Y-box protein (YB1) and recruits it to the ZEB1 promoter region and subsequently transactivates ZEB1 expression, promoting tumor growth and metastasis of pancreatic cancer in a xenograft mouse model." (PMID 36114510, 2022). "Thus, we speculate that ZEB1 O-GlcNAcylation may be involved in glucose regulated mesenchymal pancreatic cancer cells ferroptosis sensitivity." (PMID 35844792, 2022). "In the light of ZEB1 as an EMT marker, a comprehensive report determined its interaction with lncRNAs to facilitate metastasis and progression of pancreatic cancer, thus speculating that ZEB1 was apparently involved in the signalling axis initiated by LINC00472." (PMID 34363438, 2021). "High expression of ZEB1 has been observed in intrahepatic cholangiocarcinoma, colorectal cancer, gastric carcinoma, pancreatic cancer, esophageal squamous cell carcinoma and oral cavity carcinoma 6, suggesting that ZEB1 may contribute to the progression of these tumors." (PMID 33897890, 2021). "CXCR4 and ZEB1 expression is positively associated with the expression of CTLA-4 and PD-1, indicating that circ-UBAP2 might repress antigen presentation and promote immune escape in pancreatic cancer." (PMID 34496886, 2021). "ZEB1correlates negatively with ESRP1 and positively with HAS2 in NCI-60 and CCLE cellline cohorts and in lung, breast, and pancreatic tumors, indicating that feedback loops operatingamong ZEB1, ESRP1, and HAS2 may modulate cancer cell plasticity across subtypes." (PMID 31069317, 2018). "Interestingly, this study also showed that the deletion of ZEB1 freezes or halts pancreatic tumor cells in an epithelial state in which invasion, stemness, and metastatic colonization are dramatically suppressed, being cells in addition unresponsive to EMT‐inducing signals." (PMID 28590039, 2017). "It suggested those pancreatic cancer cells with lower ZEB1 expressing would lose the ability to metastasis and only those cells with higher ZEB1 expression could form liver metastasis, which might be the reason for the discrepancy of ZEB1 expression in the primary tumor and liver metastasis." (PMID 26498682, 2015). "The efficiency of this strategy was validated particularly for pancreatic cancer, by demonstrating that mocetinostat reduced ZEB1 expression, upregulated expression of miR-203 and other ZEB1 targets, and sensitized undifferentiated, ZEB1-expressing cancer cells for chemotherapy." (PMID 25872941, 2015). "Therefore, these clinical data further verified that the miR-652 might function as inhibitor in tumorigenesis of pancreatic cancer by directly targeting ZEB1." (PMID 26498682, 2015). "Since downregulation of miR-652 was associated with overexpressed ZEB1 in pancreatic cancer cells in extracellular acidity, we further explored whether restoration of miR-652 could reverse the extracellular acidity-induced EMT in pancreatic cancer cells." (PMID 26498682, 2015). "Furthermore, inhibition of Snail, Slug and ZEB-1 expression and upregulation of E-cadherin by embelin could regulate pancreatic cancer progression through its influence on reversal of EMT." (PMID 24694877, 2014). "Similarly, poorly differentiated pancreatic cancer cell lines showed higher levels of Snail and lower levels of E-cadherin compared with moderately differentiated cell lines while silencing of Zeb1 leaded to up-regulation of E-cadherin and restoration of an epithelial phenotype." (PMID 24062980, 2013).
pancreatic cancer (continued). "Importantly, in erlotinib-sensitive pancreatic cancer lines, ZEB1 protein levels were reduced." (PMID 22045191, 2012). "Interestingly, Zeb1 can also directly suppress transcription of miR-200 family members miR-141 and miR-200c indicating an interplay between Zeb1 and miR-200 family that regulates the differentiation state of pancreatic cancer cells." (PMID 24281219, 2010). "The clinical relevance of ZEB1 in PDAC patients is substantial and recognized in the complex landscape of pancreatic cancer." (PMID 41481650, 2026). "LncRNA BX111 recruits YBX1 to activate ZEB1 expression and induce EMT, promoting metastasis and progression of pancreatic cancer." (PMID 41507135, 2026). "Our study emphasizes the critical impact of ZEB1 and SNAI1 overexpression on survival rates in pancreatic cancer, primarily due to their roles in facilitating peripancreatic invasion." (PMID 41481650, 2026). "Treatment of pancreatic tumor organoids with recombinant NTN1 enhanced cell growth, epithelial-mesenchymal transition (EMT), and cancer stemness with the upregulation of ZEB1 and SOX9 through NEO1-mediated activation of focal adhesion kinase (FAK)." (PMID 40777309, 2025). "We evaluated the relationship between KLF5, ZEB1, and HMOX1 expression in tissues from pancreatic cancer patients." (PMID 39827156, 2025). "An alternative explanation is suggested by findings that experimental inactivation of core EMT-TFs in pancreatic cancer partly phenocopies TKA-organoid pEMT and that overexpression of Snail1 and Zeb1 cannot trigger EMT in the intestinal organoid model." (PMID 40393982, 2025). "This reduction correlates with increased expression of ZEB1 (zinc finger E-box binding homeobox 1), a key inducer of EMT that down-regulates E-cadherin in pancreatic cancer cells." (PMID 39200178, 2024). "The anti-tumor effect of PRMT1 downregulation is reversed by overexpression of ZEB-1, indicating the role of PRMT1–ZEB1-signaling cascade in pancreatic cancer progression." (PMID 38612768, 2024). "In pancreatic cancer, the transcriptional silencing of SIRT3 by zinc finger E-box binding homeobox-1 (ZEB1) in cooperation with the methyl-CpG-binding domain protein 1 (MBD1) promotes a metabolic shift towards glycolysis." (PMID 39682281, 2024). "Preca and colleagues reported a self-enforcing CD44s/ZEB1 feedback loop that maintains EMT and stemness properties in breast and pancreatic cancer cells." (PMID 38139138, 2023). "Thereby, ZEB1 controls CD44s splicing by repression of ESRP1 in breast and pancreatic cancer, whereby CD44s itself activates ZEB1 expression." (PMID 38139138, 2023). "In gemcitabine-resistant pancreatic cancer, the EMT process was significantly inhibited when ZEB1 and LOXL2 were co-regulated." (PMID 37737908, 2023). "As shown, in pancreatic cancer tissues MXRA5 is co-expressed with a number of key ECM-TFs, including Zeb1, Zeb2, Twist and Slug." (PMID 36828810, 2023). "MiR-4269, modulating ZEB1/OTX1 axis, exerts tumor inhibitory effects on pancreatic cancer progression and offers a new insight into the clinical treatment of pancreatic cancer patients." (PMID 38069286, 2023). "The overexpression of ZEB1 results in the enhanced migration, invasion, and EMT of pancreatic cancer cells." (PMID 37686338, 2023). "After Numb PRRL specific knockdown, the expression of E-cadherin was up-regulated, while the expression of N-cadherin, Vimentin, Fibronectin, Snail2 and ZEB1 were down-regulated, suggesting that Numb PRRL can promote EMT in pancreatic cancer cells." (PMID 35345586, 2022). "Zinc finger E-box-binding homeobox 1 (ZEB1) is a transcription factor that reportedly promotes cancer proliferation in lung adenocarcinoma 37, HCC 38 and pancreatic cancer." (PMID 36168636, 2022). "ZEB1 recruits the histone deacetylases HDAC1 and HDAC2, which inhibit E-cadherin expression in pancreatic cancer." (PMID 36499447, 2022).
pancreatic cancer (continued). "So, in the present study, the qRT-PCR and western blotting assays were applied to examine the differential expression level of linc00511, p21, Snail, and ZEB1 between HPDE6-C7 and pancreatic cancer cells." (PMID 35794978, 2022). "Surprisingly, SOX9 overexpression did not alter the expression of SNAIL or other well-known EMT transcription factors such as SLUG or ZEB1 in BxPC-3 and IMIMPC-2 pancreatic cancer cells; however, the expression of the BMI1 stem cell factor was elevated." (PMID 35205666, 2022). "In a separate project in our laboratory, we determined a role of ROCK2 in EMT-induced gemcitabine resistance in pancreatic cancer cells, and we revealed that ROCK2 induced increasement of ZEB1 expression and enhancement of DNA repair system." (PMID 35145081, 2022). "Another study reports that, miR-429 expression is down-regulated in pancreatic cancer, and miR-429 exerts an effect on the migration, invasion and EMT of pancreatic cancer by regulating ZEB1 expression." (PMID 35468721, 2022). "For example, EMT-TFs (ZEB1, SNIAL, SLUG) have been demonstrated to confer resistance to oxaliplatin and cisplatin in breast, ovarian, colon, and pancreatic cancers." (PMID 34350177, 2021). "In pancreatic cancer, the application of the HDAC class I inhibitor mocetinostat results in de‐repression of ZEB1‐inhibiting miRNAs, ZEB1 downmodulation, MET, and resensitization to gemcitabine in mice." (PMID 34459003, 2021). "For example, gemcitabine‐resistant Panc1 pancreatic cancer cells exhibit EMT characteristics and become sensitized upon ZEB1 knockdown." (PMID 34459003, 2021). "To sum up, we concluded that ZEB1 binds to the region between −641 and −631 bp of the ELK3 promoter to activate its’ transcriptional activity in pancreatic cancer." (PMID 34409034, 2021). "MiRNA-200c and miRNA-141 are downregulated in pancreatic cancer cell lines and act in an EMT-inhibitory manner being engaged in reciprocal suppressive interactions with Zeb1." (PMID 34771695, 2021). "In pancreatic cancer, another study revealed that circ-UBAP2 and hsa-miR-494 can modulate the expression of CXCR4, HIF1A, ZEB1, and SDC1." (PMID 34496886, 2021). "ZEB1, as the core EMT inducer, is a pivotal factor in tumorigenesis, invasion and metastasis in pancreatic cancer." (PMID 34409034, 2021). "On the other hand, EGCG suppresses invasion and migration by preventing the cadherin switch and decreasing the expression level of TCF8/ZEB1, β-catenin, and vimentin in pancreatic cancer." (PMID 34744708, 2021). "Meanwhile, both were found to be overexpressed in pancreatic cancer tissues and high ZEB1 and ELK3 expression were both closely associated with patients’ clinicopathological features and worse overall survival, indicating ZEB1 and ELK3 may be efficient diagnostic and therapeutic targets in PDAC." (PMID 34409034, 2021). "In pancreatic cancer, KDM4B has been shown to regulate ZEB1 expression during TGF-β -induced EMT, and silencing KDM4B can significantly inhibit the migration and invasion of pancreatic cancer cells and EMT." (PMID 35186950, 2021). "Very strikingly, in pancreatic cancer, TGFβ‐mediated EMT depends almost exclusively on ZEB1, since Zeb1 knockout in KPC cells blocks more than 90% of TGFβ‐induced alterations in gene expression, despite of Snai1 upregulation during TGFβ treatment." (PMID 34459003, 2021). "In the presence of isolated effector CD4+ T cells, pancreatic cancer cells show upregulation of VIM, L1CAM and ZEB1, combined with a more migratory phenotype, which was reverted by blocking IL6 and TNFα." (PMID 34459003, 2021). "In gemcitabine-resistant pancreatic cancer cells (MiaPaCa-2), DIM upregulated the expression of E-cadherin and suppressed zinc finger E-box binding homeobox 1 (ZEB1), vimentin, and slug, leading to a reversal of epithelial-to-mesenchymal transition." (PMID 35582221, 2020).